NRP1 (neuropilin 1)
Diseases named in the same sentence as NRP1 in open-access papers (continued):
Sharing a sentence is not in itself a finding about the gene and the disease.
pancreatic cancer (continued). "Neuropilin-1 is expressed in pancreatic cancer, but not in nonmalignant pancreatic tissue." (PMID 15956974, 2005). "In a normal pancreas, there is an absence of NRP1 and a presence of NRP2 in the endocrine islets and acinar cells, while in pancreatic cancer cells, both NRP1 and NRP2 are highly expressed." (PMID 40277760, 2025). "The study of Sema3A and its receptors, such as plexinsA1-A4 (PLXNA1-A4) and neuropilin-1 (NRP1) in PC, demonstrates that SEMA3A had no impact on the growth or survival of pancreatic tumor cells and was upregulated in PC." (PMID 36713527, 2022). "Neuropilin-1 (NRP-1) is a non-tyrosine kinase transmembrane receptor and has drawn great attention in cancer research, since it is highly expressed in gastrointestinal cancers, including pancreatic cancer." (PMID 31572065, 2019).
viral infection (55 papers, 2010 to 2025). "The NRP-1/VEGF-A axis has been implicated in the pathogenesis of several viral infections, such as those caused by human T cell lymphotropic virus type 1 (HTLV-1) and Epstein-Barr virus (EBV)." (PMID 40008234, 2024). "The two viral infections in which the NRP-1/VEGF-A axis has been implicated most strongly are, however, SARS-CoV-2 and HIV." (PMID 40008234, 2024). "The other viral infection in which the NRP-1/VEGF-A axis has been implicated is HIV." (PMID 40008234, 2024). "We therefore hypothesized that increased systemic TGF-β1 expression, as seen in the blood samples taken from patients with severe cardiac fibrosis, might also predispose to viral infection of the lung due to increased pulmonary expression of NRP-1, which facilitates SARS-CoV-2 cell entry." (PMID 34745111, 2021). "The binding of the spike protein to the b1 domain of NRP1 has been shown to enhance viral infection twofold." (PMID 39908250, 2025). "This highlights the potential role of NRP1 in facilitating viral infection in the CNS and contributing to neuro-pathogenesis." (PMID 40431631, 2025). "Further research of NRP-1-induced modulations of specific signal transduction pathways in viral infection is warranted, as these pathways (e.g., the Akt and the MAPK/ERK signalling pathways) are associated with cell proliferation, survival, and migration." (PMID 37759529, 2023). "Results from in vitro infection assays demonstrate that Nrp1 expressed on HTLV-1-infected cells inhibits viral infection." (PMID 37375521, 2023). "NRP-1 is also implicated in the immune response to viral infection, as NRP-1 is expressed on regulatory T-lymphocytes, and the therapeutic manipulation of these cells depends on the surface receptors, including NRP-1." (PMID 37759529, 2023). "Studies based on publicly available transcriptome databases revealed that one of the most likely enhancers of direct viral infection in the brain is NRP1, which is highly expressed in multiple neuron and glial cell types, including astrocytes and microglia." (PMID 37458167, 2023). "Our results showing that CNTN1 promotes ACE2-dependent infection echoes previous findings on NRP1, and further supports the existence of additional co-factors that promote viral infection." (PMID 35931765, 2022). "The high expression of NRP1 in olfactory epithelial cells can be observed in patients with COVID-19, suggesting its role in potentiating viral infection and being the target of therapies to control the disease." (PMID 36439786, 2022). "As immune disorder plays an important role in both oncogenesis and virus infection, the correlation between NRP1 expression and immune infiltration levels was further investigated." (PMID 36338984, 2022). "After cleaved by furin, the fragment S1 containing the C-terminus (CendR) binds to the domain b1 of NRP1, contributing to the elevated virus infection process." (PMID 36439786, 2022). "On the other hand, NRP-1, which is linked with the development of AIS, is also associated with different viral infections." (PMID 36009579, 2022). "There is a growing appreciation for roles played by NRP1 in the immune response, especially in the function of regulatory T cell response to virus infection." (PMID 34249735, 2021). "The first step of viral infection relies on successive binding of the surface gp46 to heparan sulfate proteoglycans (HSPGs), neuropilin-1 (NRP-1), and the glucose transporter type 1 (GLUT-1), expressed on target cells." (PMID 33348900, 2020). "We show that Nrp1 is highly upregulated on CD8 T cells during the acute phase of viral infection and that deletion of Nrp1 during this window skewed the T cells more toward memory precursors than terminally differentiated effector cells." (PMID 31118303, 2019). "Following viral infection, NRP1 was moderately upregulated in effector and memory CD8+ T cells compared with naïve cells." (PMID 29067024, 2017).
viral infection (continued). "This small subpopulation of Nrp1+ DCs is importantly involved in combating viral infections, and responds by producing large amounts of interferon α (IFN-α)." (PMID 22948112, 2012). "The study found that targeting the interaction between the SARS-CoV-2 spike protein and the neuropilin-1 (NRP1) b1 domain could effectively reduce viral infection." (PMID 39908250, 2025). "Consequently, targeting NRP1 to disrupt this interaction represents a promising strategy to mitigate viral infection." (PMID 39908250, 2025). "From a biophysical point of view, this fact may indicatethat NRP1 is less effective in viral infection compared to ACE2." (PMID 39010661, 2024). "Considering the low efficiency of NRP1 as an entry receptor, it could be speculated that a threshold of expression is necessary to allow viral infection." (PMID 37350967, 2023). "COL4A1 and GEM are genes involved in viral infection, while NRP1, which encodes neuropilin 1 (Nrp1), serves as an HTLV-1 receptor on target cells but has no reported function on HTLV-1-infected cells." (PMID 37375521, 2023). "Indeed, enriched gene ontology analysis revealed that genes involved in the cellular response to cytokines, viral infection or T cell differentiation were differentially expressed by Nrp-1+ and Nrp-1- CD8+ T cells from PbA-infected mice." (PMID 38019895, 2023). "In parasitic and acute viral infections, the role of Nrp-1 expression on CD8+ T cells remains unclear." (PMID 38019895, 2023). "Hence, induction of Nrp-1 expression on CD8+ T cells appears to be a general mechanism in acute parasitic and viral infections associated with exacerbated disease severity." (PMID 38019895, 2023). "While HBZ has been found to enhance HTLV-1 infection using cell-based models, there may be certain circumstances in which activation of Nrp1 expression negatively impacts viral infection, which is discussed." (PMID 37375521, 2023). "Spatial correlation of RSFA abnormality with the expression of ACE2 and Neuropilin-1, or of genes involved in cellular responses to viral infection would have provided supportive evidence of a role for direct viral infection as a mechanism, but we were unable to demonstrate such correlations." (PMID 36451358, 2022). "Our finding added evidence to the idea that ACE2 was not the only receptor involved in the infection process of SARS-CoV-2, NRP1 may also contribute to virus infection and virulence." (PMID 36338984, 2022). "In addition, we also profiled the expressions of the known cofactors of ACE2, i.e., TMPRSS2, FURIN, and NRP1, which also play roles during the viral infection and are also conserved between human and the mammalian species investigated above." (PMID 33392409, 2021). "Since interferons are crucial for successfully combating viral infections, it has been hypothesized that NRP1-mediated IFN-α secretion in pDCs may affect virus clearance in vivo." (PMID 29067024, 2017). "Targeting DC and interfering with NRP-1 signalling might have several other consequences on viral infection." (PMID 21114861, 2010). "As such, NRP1 may increase viral infection by SARS-CoV-2 in the presence of other host factors like ACE2, and it may also initiate receptor-dependent viral internalization, potentiate severe immune-pathological inflammation, and lead to a systemic spread of the infection, independently of ACE2." (PMID 34360529, 2021). "We infected C57BL/6 mice with PbA or LCMV strain WE (LCMV-WE) and analyzed the T cell phenotype and the influence of Nrp-1 expression on manifestation of ECM and liver damage during acute viral infection." (PMID 38019895, 2023). "The expression and role of Nrp-1 on CD8+ T cells during parasitic and acute viral infections remain elusive." (PMID 38019895, 2023). "The molecule neuropilin-1 (NRP1) plays an important and complex role in the secondary CD8 T-cell response to control viral infections and tumors." (PMID 36773052, 2023).
viral infection (continued). "Given the overall positive role of HBZ toward viral infection, we speculate that negative effects on infection caused by the activation of Nrp1 might only arise during specific stages of HTLV-1 pathogenesis, such as progression from an indolent to an aggressive form of ATL, which is discussed." (PMID 37375521, 2023). "Although out of the scope of this study, these interesting differences suggest that distinct residues are involved in the interaction with NRP1 and NRP2, perhaps implying differential roles during viral infection." (PMID 35931765, 2022). "NRP1 depletion with RNAi targeting Nrp1 mRNA inhibits the binding of the SARS-CoV-2 spike protein to NRP1 and, consequently, decreases the rate of viral infection." (PMID 34745215, 2021). "For viral infection, Glucose Transporter 1 (GLUT1), Heparan Sulfate Proteoglycans (HSPG) and Neuropilin 1 (NRP-1) have been identified as the HTLV-1 receptor complex important for viral binding and cellular entry." (PMID 30042514, 2018). "ACE2 and NRP1 as the host viral receptors for the S-protein of SARS-CoV-2 binding triggers the viral infection and enter host cells, so one promising strategy to prevent SARS-CoV-2 infection is interrupted or blocked the interaction between S-protein and ACE2/NRP1." (PMID 38765079, 2024). "NRP-1 plays a multisystem role that can make it an ideal entry target for SARS-CoV-2 and could contribute to the multisystem impact of viral infection." (PMID 40008234, 2024). "Moreover, NRP1 also facilitated other viral infections, such as the (EBV), the PRV, the mCMV, the HTLV-1 and HTLV-2, and CD inhibited NRP1 expression and viral syncytial formation, highlighting therapeutic significances for anti-different viruses." (PMID 38138098, 2023). "We found that the expression of Nrp1 on HTLV-1-infected T-cells and HTLV-1-producing cells was associated with decreased viral infection without any significant effect on viral production." (PMID 37375521, 2023). "Based on these findings, simultaneously inhibiting S-RBD and NRP1 may result in a synergistic effect on the inhibition of virus infection, and dual S-RBD/NRP1-targeting inhibitors may become a potential therapeutic approach to preventing SARS-CoV-2 infection." (PMID 37194732, 2023). "However, BSG KO and NPR1 KO kidney organoids clearly supported viral infection as demonstrated by confocal microscopy and TEM analysis, thus excluding an essential role of BSG or NRP1 in renal SARS-CoV-2 infections." (PMID 35561674, 2022). "Neuropilin-1 has been suggested as a coreceptor for SARS-CoV-2 S and may be important for the viral infection infiltrating the neuronal network." (PMID 34157282, 2021). "Nrp1 appears to have a functional role in pDCs, because the incubation of these cells with an anti-Nrp1 antibody (BDCA-4) blocked IFN-α production induced by viral infection or nucleic acids." (PMID 22948112, 2012). "Therefore, the potential interactions between CD147, DPP4, NRP1, and ACE2 could form a receptor network that facilitates and amplifies viral infection." (PMID 40431631, 2025). "Given that it had been shown that NRP1, which is known to bind furin-cleaved substrates, potentiating SARS-CoV-2 infectivity, we analyzed in our cell system whether the decreased expression of NRP1 decreased viral infection." (PMID 40872854, 2025). "Thus, whether Nrp-1 might also have an impact on the migratory capacity of pathologic CD8+ T cells during parasitic and viral infections in addition to its effect on the cytotoxic activity has to be clarified in further studies." (PMID 38019895, 2023). "However, the function of Nrp-1 on CD8+ T cells in acute parasitic and viral infections remains unclear." (PMID 38019895, 2023).
viral infection (continued). "Additionally, in cells with low ACE2 expression, viral infection can be enhanced by additional host factors, such as the extracellular protease BSG (also known as CD147), the transmembrane receptor NRP1, lectins, or HAVCR1 phosphatidylserine receptors such TIM-1 (also known as TIMELESS) and AXL." (PMID 37458167, 2023). "We similarly found that Nrp1 is incorporated into HTLV-1 virions, and consistent with the hypothesis of steric inhibition, an Nrp1 mutant lacking most of the ectodomain did not reduce viral infection." (PMID 37375521, 2023). "In contrast, in the context of expression by the infected cell, whether Nrp1 participates in viral infection is not known." (PMID 37375521, 2023). "However, viral infection did not seem to be particularly affected by reduced levels of the ACE2 and NRP1 proteins in the MDA-MB-231 and HCC1937 cell lines." (PMID 38849411, 2024).
prostate carcinoma (50 papers, 2003 to 2024). A carcinoma that arises from epithelial cells of the prostate gland. "NRP1 expression has been associated with the metastatic potential of prostate cancer cells; more aggressive cell lines such as DU145 or PC-3 exhibit higher expression levels compared to less aggressive cell lines and benign hyperplasia cells." (PMID 38903533, 2024). "NRP1 is associated with tumor progression; it is strongly expressed in lung, brain, colon, ovarian, and prostate cancers with poor patient prognoses." (PMID 26209534, 2015). "NRP1 has been reported to be up-regulated in many tumour types, and some clinical studies have shown that NRP1 overexpression is positively associated with metastatic potential, advanced stage, and clinical grade in prostate carcinoma, gastrointestinal carcinoma and colorectal carcinoma." (PMID 22926477, 2012). "Previous studies have reported NRP1 overexpression in tumoral prostate cancer cell lines such as LNCaP, DU145, and PC-3, compared with benign prostatic epithelial cell lines cultured on conventional tissue culture plates." (PMID 38903533, 2024). "NRP1 and MET are physically associated on the plasma membrane of prostate cancer cells, and in response to VEGF stimulation, their interaction significantly facilitates further recruitment and activation of MET." (PMID 39354638, 2024). "Earlier experiments exploring how NRP1 influences cancer growth show that a soluble NRP1 (sNRP1) isoform used as a tool to inhibit NRP1 activity induces vascular damage, hemorrhage, and apoptosis in tumors from rat prostate cancer cells." (PMID 37894289, 2023). "Upregulation of NRP1 is prognostic of metastatic progression and patient mortality in prostate cancer." (PMID 37894289, 2023). "In prostate cancer, shRNA-mediated suppression of NRP-1 regulated the invasiveness and metastatic dissemination of cancer cells in vivo and NRP-1 expression was established as an independent marker of metastasis and cancer-specific survival." (PMID 33884469, 2021). "The Perlecan-Semaphorin 3A-Plexin A1-Neuropilin-1 (PSPN) Complex at the cell surface of prostate cancer (PCa) cells influences cell–cell cohesion and dyscohesion." (PMID 33809984, 2021). "We have previously demonstrated that GBX2 directly targets NRP1 in human prostate cancer cells (PC-3)." (PMID 33322598, 2020). "Another interesting study revealed NRP1 upregulation in the adaptive response of prostate cancer (PCa) to androgen-targeted therapy." (PMID 31027288, 2019). "A few reports indicated that NRP-1 downregulation or antagonism inhibited migration and enhanced chemosensitivity in non-small cell lung, kidney or prostate cancer and osteosarcoma cells." (PMID 29728077, 2018). "NRP-1 overexpression has been reported in a variety of human cancers, including those derived from carcinomas of the prostate, kidney, bladder, stomach, colon, pancreas, breast, ovary, lung, liver, nasopharynx, and brain." (PMID 25873749, 2015). "In a recent paper, NRP1 was found to drive EMT process by promoting Snail1 nuclear localization in prostate cancer cells." (PMID 21747928, 2011). "In a prostate cancer model, transfection of NRP-1 increased VEGF165 binding, basal cell motility, and tumour size in vivo, suggesting that the receptor functions in a VEGF-dependent fashion to enhance tumorigenicity." (PMID 15956974, 2005). "Overexpression of NRP-1 in prostate carcinoma cells enhances angiogenesis and increases proliferation of ECs, suggesting that the expression of NRP-1 by tumour cells themselves can influence tumour growth and angiogenesis." (PMID 12618892, 2003). "Various tumour cell types, such as breast and prostate cancers, express abundant levels of NRP-1 mRNA, whereas low levels of NRP-1 are found in some normal adult tissues." (PMID 12618892, 2003).
prostate carcinoma (continued). "NRP-1 is also expressed by several types of tumour cells, such as breast and prostate cancers, and overexpression of NRP-1 in prostate carcinoma cells has been shown to enhance tumour angiogenesis and growth." (PMID 12618892, 2003). "But SEMA3C binds to NRP1 to promote prostate cancer cell perineural invasion by activating cMET." (PMID 37701532, 2023). "Moreover, the latest literature also indicated that NRP1 promotes prostate cancer progression via modulating the EGFR-dependent AKT pathway activation." (PMID 37190154, 2023). "Moreover, NRP-1 expression appears to correlate with advanced stage or grade in prostate cancer and astrocytoma." (PMID 12618892, 2003). "However, opposite results have been observed, describing a decrease in NRP1 expression through autophagy in hypoxia in breast and prostate carcinoma cells, while raised levels were observed under hypoxia in cervical cancer, lung adenocarcinoma and oral squamous cell carcinoma." (PMID 36376373, 2023). "Interestingly, MAO-A promotes prostate cancer cell PNI through SEMA3C/PlexinA2/NRP1-cMET signaling." (PMID 36418844, 2023). "Consistent with this, in prostate cancer, the SEMA3C/PlexinA2/NRP1 axis has been shown to be correlated with PNI and nerve density within the tumor cancer model." (PMID 37719704, 2023). "The expression of sema3C, NRP-1, and plexin-A2 is upregulated by monoamine oxidase A (MAOA) in prostate cancer cells." (PMID 37627074, 2023). "In prostate cancer PC3 cells, NRP-1 downregulation was correlated with the impaired ability of the cells to metastasize to the lungs upon nordihydroguaiaretic acid treatment." (PMID 37175499, 2023). "In Dunning rat prostate carcinoma cell lines, sNRP1 inhibited VEGF165 binding to full-length NRP1, and its overexpression inhibited tumor growth and elicited apoptosis in vivo." (PMID 31027288, 2019). "Taken together, these data suggest that Plexin B1 and coreceptors, NRP1 and NRP2, mediate SEMA3C signaling in prostate cancer cells." (PMID 29348142, 2018). "In contrast, it was reported that perlecan interacts with a complex of sema3A, plexin-A1, and NRP-1 on the cell surface of prostate cancer cells and that cleavage of this complex by MMP-7 cell-cell bonds promotes the metastatic dissemination of prostate cancer cells." (PMID 37627074, 2023). "We further determined whether DCN-tCRK binds to the cells that express NRP-1, i.e., human PC3 prostate carcinoma cells." (PMID 32497513, 2020). "NRP-1 expression has been correlated to metastasis in tumor tissue from prostate cancer patients only, not breast cancer." (PMID 28607365, 2017). "Human prostate carcinoma DU145 cells, which express NRP1 but not VEGFR-2, were then used to examine cell growth in response to chemotherapy." (PMID 20087344, 2010).